FDX1 (ferredoxin 1)
Diseases named in the same sentence as FDX1 in open-access papers (continued):
Sharing a sentence is not in itself a finding about the gene and the disease.
cancer (continued). "Finally, 6 COAD patients with high expression of FDX1 were screened, and the proportion of CD8+ T cells in cancer tissues of these patients was significantly higher than that in paracancerous, while the CD4+ T cells presented the opposite pattern." (PMID 36173462, 2023). "We found that in 20 pairs of ccRCC and adjacent nontumor tissues, the expression of FDX1 in 19 adjacent tissues was higher than in cancer tissues." (PMID 36105937, 2022). "In contrast, FDX1 expression was negatively correlated with the levels of mast cells resting in BRCA, LGG, and STAD, while it was positively correlated with mast cells activated in these cancers." (PMID 36210836, 2022). "Although mounting evidence supports a vital role for FDX1 in tumorigenesis of some cancers, no pan-cancer analysis of FDX1 has been reported." (PMID 36210836, 2022). "FDX1 expression was significantly correlated with MSI in 8 tumors: it was positively correlated in HNSC, KIRC, STAD, and UCEC, and negatively in the other four cancers." (PMID 36210836, 2022). "In contrast, FDX1 and MTF1 expression in most cancers were lower than paired normal tissues." (PMID 36518756, 2022). "The differences in FDX1 expression between ccRCC and nonneoplastic tissues adjacent to cancer were analyzed by R software." (PMID 36105937, 2022). "In addition, we assessed the relationship between FDX1 expression and PFI, a measure of how well cancer responds to palliative care." (PMID 36210836, 2022). "Therefore, we investigated the pan-cancer relationship between TME and FDX1 expression, using the ESTIMATE algorithm to calculate the stromal and immune cell scores in pan-cancer." (PMID 36210836, 2022). "On the contrary, KIRCs were found to potentially have a lower copper cell death in cancer tissue because their anti-cuproptosis gene ATP7B was upregulated with pro-copper metabolism-related cell death genes SLC31A1, FDX1, DLAT, and LIAS downregulated in cancer tissues." (PMID 36276096, 2022). "Correlation analysis of FDX1 with checkpoint gene expression found a high correlation (p < 0.05) with tumor necrosis factor (TNF)–related immune genes (TNFRSF14, 15, 25) and CTLA4, PDCD1, CD274, NRP1, and VTCN1 in some kinds of cancers." (PMID 36061184, 2022). "In addition, FDX1 expression was also significantly correlated with immune cell infiltration, immune-related genes, TME, and drug resistance in various cancers." (PMID 36210836, 2022). "In both groups, the expression of FDX1 in adjacent nonneoplastic tissues to ccRCC tissues was higher than in cancer tissues (P < 0.05)." (PMID 36105937, 2022). "Next, we conducted gene co-expression analyses to explore the relationship between FDX1 expression and immune-related genes, including chemokine, chemokine receptor, MHC, immunostimulatory, immunosuppressive, and immune checkpoint-related genes, in pan-cancer." (PMID 36210836, 2022). "We highlight that there are not studies in cancer for FDX1, MULT, VAMP4 and DENND4A genes or its protein products." (PMID 33265245, 2018). "Moreover, FDX1 serves as a key regulatory factor for protein lipoylation through direct binding to LIAS and plays a role in metabolic conditioning-induced cell death in cancer cells." (PMID 39360273, 2024). "However, the role that FDX1 plays in human cancer prognosis and immunology is still not well understood." (PMID 37193786, 2023). "Whether FDX1 could function in the pathogenesis of distinct multiple cancer types based on potential molecular mechanisms has not been well described." (PMID 37298135, 2023). "However, FDX1 has not mainly been elucidated in cancer, and its role in tumorigenesis or pan-cancer is still unclear." (PMID 36210836, 2022). "Our data showed that FDX1 had a negative relationship with NK cells activated in most cancers." (PMID 36210836, 2022). "This suggested that FDX1 might serve as a potential regulatory target in immunotherapy for these cancers, and it also implied a non-negligible role in the induction of immune cell recruitment." (PMID 35991547, 2022).
cancer (continued). "The expression of FDX1 was not significantly different in most cancers by clinical stage, age, and gender, but in some cancers, especially ACC, KIRC, HNSC, MESO, and THCA, it could serve as an independent prognostic factor and a potential prognostic marker." (PMID 35991547, 2022). "There were positive and negative correlations of FDX1 and PDHA1 with CD8+ T cell infiltration found in pan-cancers, while there were two negative correlations for TCGA-STAD." (PMID 36895378, 2023). "The existing literature has not confirmed the direct relationship between FDX1 and NLRP3, but researchers suggested that ATP7A and NLRP3 are negatively correlated in pan-cancer." (PMID 37138870, 2023). "Results showed that the cancer–noncancer protein expression patterns of ATP7B, SLC31A1, DLAT, and LIAS were mostly consistent with the patterns at the mRNA level but that of FDX1 was not." (PMID 36276096, 2022). "For example, the expression of DLAT, LIAS, and ATP7B was negatively correlated with the methylation in most of the cancer types, while the expression of SLC31A and FDX1 was not remarkably correlated with the methylation in most of the cancer types." (PMID 36276096, 2022). "Among these cancer types, SKCM, PAAD, LUSC, LUAD, FDX1 expression, and MSI had a significant negative correlation, and the PAAD coefficient was the highest; conversely, in DLBC, HNSC, KIRC, STAD, and UCEC, FDX1 expression was positively correlated to MSI, and the DLBC coefficient was the highest." (PMID 36061184, 2022).
infection (2 papers, 2023 to 2025). The state of being infected such as from the introduction of a foreign agent such as serum, vaccine, antigenic substance or organism. "Ferredoxin 1 has been reported to interact with p25 of potato virus X (PVX) and inhibit its infection in tobacco." (PMID 37175719, 2023).
metabolic disorders (2 papers, 2022 to 2025). "Because ccRCC is a highly associated metabolic disease with mitochondrial function, the role of FDX1 in ccRCC is largely unknown." (PMID 36186457, 2022). "In previous studies, it was found that deletion of FDX1 and LIAS conferred resistance to copper-induced cell death, but it has also been shown that defects in neonatal LIAS are associated with severe metabolic disorders." (PMID 40337173, 2025). "The PPI analysis indicated that downregulated FDX1 expression in ccRCC may contribute to mitochondrial biogenesis disorders, metabolic disorders, and oxidative stress." (PMID 36186457, 2022).
cardiovascular diseases (1 paper, 2022). "The results showed that in addition to its involvement in tumors, FDX1 was also involved in cardiovascular diseases, respiratory diseases, and endocrine system diseases." (PMID 36226187, 2022).
immune dysfunction (1 paper, 2023). "In our study, TIDE analysis showed that in the group with low FDX1 expression, poor response to ICIs might be related to higher TIDE scores, immune dysfunction, and immune exclusion." (PMID 37432054, 2023).
FDX1 also shares sentences with these, for which no sentence is quoted: rectum adenocarcinoma (7 papers); kidney chromophobe (6); breast invasive carcinoma (5); bladder urothelial carcinoma (4); endocervical adenocarcinoma (4); pancreatic adenocarcinoma (4); esophageal squamous cell carcinoma (3); head and neck cancer (3); head and neck squamous cell carcinoma (3); kidney cancer (3); pheochromocytoma and paraganglioma (3); prostate adenocarcinoma (3); skin cutaneous melanoma (3); uterine carcinosarcoma (3); colorectal adenocarcinoma (2); Depression (2); diabetes (2); germ cell tumor (2); lymphoid neoplasm (2); seminoma (2); adenocarcinoma (1); Alzheimer disease (1); asthma (1); bone cancer (1); bone disorder (1); clear cell carcinoma (1); colon polyps (1); endocrine system diseases (1); epidermoid carcinoma (1); epilepsy (1).
A further 26 diseases each share a sentence with FDX1 in 1 paper.